TNF (tumor necrosis factor)
Diseases named in the same sentence as TNF in open-access papers (continued):
Sharing a sentence is not in itself a finding about the gene and the disease.
chronic kidney disease (continued). "SDMA in chronic kidney disease (CKD) patients was more significantly correlated to interleukin (IL)-6 and tumor necrosis factor-alpha (TNF-α) levels compared to ADMA." (PMID 31357472, 2019). "Myostatin contributes to inflammatory conditions such as chronic kidney disease, and therapeutic blockage reduces immunopathology through the suppression of IL-6, IFN-γ and TNF-α." (PMID 26291724, 2015). "We studied the association of inflammatory biomarkers including C-reactive protein (CRP), tumor necrosis factor-alpha (TNF-α), and interleukin-6 (IL-6) with chronic kidney disease (CKD)." (PMID 26025192, 2015). "Elevated plasma SDMA levels were found to correlate with inflammatory markers, such as TNF-alpha, high sensitivity CRP and Interleukin-6 (IL-6) in chronic kidney disease (CKD) patients." (PMID 23443106, 2012). "In chronic kidney disease receiving hemodialysis, when compared with placebo, curcumin had a non-significant effect on IL-6 (SMD:0.24%; 95% CI: 0.14, 0.62; I2 = 97.1%), TNF-a (SMD:0.11; 95% CI: 0.19, 0.40; I2 = 95.9%) or hs-CRP (SMD: 0.17%; 95%CI: 0.36, 0.03; I2 = 79.6%)." (PMID 40538540, 2025). "While methylprednisolone use and chronic kidney diseases were significant predictors of mortality in the anti-TNF group, no traditional baseline characteristics independently predicted mortality in the anti-IL6 group, except the final therapy received." (PMID 40700294, 2025). "According to the previous studies, DN was accompanied by the increased amount of pro-inflammatory cytokines and chemokines, including tumor necrosis factor-α(TNF-α), interleukin (IL)-1βand IL-6.It has reported that HIF-PHIs can reduce inflammation and oxidative stress in chronic kidney disease." (PMID 36843948, 2023). "Fourth, Inflammation.In patients with chronic kidney disease, an independent negative correlation between inflammatory cytokines (TNF-α, IL-6 and CRP) and FT3 was found." (PMID 37821807, 2023). "In addition, treatment with melanin prevented adenine-induced chronic renal failure in mice and cisplatin-mediated nephrotoxicity by suppressing MAD, upregulating GSH, SO, GPx, and CAT, and inhibiting the production of TNF-α and IL-6." (PMID 36838869, 2023). "In the Chronic Renal Insufficiency Cohort (CRIC) study, an inverse relationship between biomarkers of inflammation (interleukin-1β, interleukin-1 receptor antagonist, interleukin-6, tumor necrosis factor-α, C-reactive protein, and fibrinogen) and renal function was advocated." (PMID 33466271, 2021). "Both of GA and AA genotypes of TNF−α −376 G/A (rs1800750) SNP, serial third estimation levels of urea and sCr, comorbidity of DM, and chronic kidney disease were predictors of non-survival by univariant analysis (p < 0.05)." (PMID 34692772, 2021). "Several of these circulating cytokines including TNF-α and IL-6 are higher in patients with chronic renal failure and this can occur even in the absence of aging." (PMID 30274250, 2018). "In experimental chronic renal failure, a correlation was found between elevated levels of TGF-β1 and TNF-α with cardiac fibrosis, which may indicate the involvement of these biomarkers in pathogenesis of CVD in CKD." (PMID 27034745, 2016). "Plasma levels of interleukin (IL)-1β, IL-1 receptor antagonist (IL-1RA), IL-6, tumor necrosis factor (TNF)-α, transforming growth factor (TGF)-β, high-sensitivity C-Reactive protein (hs-CRP), fibrinogen and serum albumin were measured in 3,939 Chronic Renal Insufficiency Cohort study participants." (PMID 25909952, 2015). "In conclusion, BSHX reduces the levels of Scr and BUN, inhibits in situ expression of FN and LN, increases the mRNA expression of PPARγ, and decreases the mRNA expression of TNF-α, NF-κB, OPN, TGF-β1, and CTGF in the kidney tissue of rats with chronic renal failure." (PMID 24864155, 2014).
chronic kidney disease (continued). "Moreover, patients with chronic kidney disease (CKD) exhibit significantly reduced Klotho levels accompanied by elevated inflammatory cytokines, including interleukin-6 (IL-6) and tumor necrosis factor-alpha (TNF-α)." (PMID 40519908, 2025). "Common comorbidities, including obesity, diabetes, hypertension, chronic obstructive pulmonary disease (COPD), and chronic kidney disease (CKD), have been postulated to drive the systemic inflammatory state, as shown by elevated levels of circulating cytokines, including IL-1β, IL-6, CRP, and TNFα." (PMID 36818566, 2023). "Proinflammatory cytokines such as TNFα, IL-1β, and IL-6 are potent stimuli for the FGF-23 secretion by osteocytes and have been demonstrated to play a role in upregulating intact FGF23 in experimental models in vivo of both acute kidney injury and chronic kidney disease." (PMID 37893926, 2023). "In chronic renal failure rats, TFA administration improved renal injury, remodeled gut microbiota dysbiosis, including regulated intestinal-derived metabolites such as D-serine, D-amino acid oxidase, L-serine, and serine racemase, suppressed the levels of pro-inflammation (TNF-α and IL-1β)." (PMID 35123452, 2022). "Carbamylated darbepoetin (recombinant human erythropoietin) or darbepoetin (100 ng/ml) could decrease telomere shortening and senescence induced by TNF-α and uremic serum in EPCs from non-dialysis chronic kidney disease patients." (PMID 34712416, 2021). "Visceral adipocytes have been shown to produce an array of adipocytokines that could contribute to endothelial injury in the kidney influencing progression to chronic kidney disease (CKD), such as angiotensinogen, TNF-α, plasminogen activator inhibitor-1, resistin, ghrelin, and leptin." (PMID 31152254, 2019). "Similarly, pentoxifylline failed to significantly reduce serum TNF-α levels in patients with chronic kidney disease." (PMID 26300986, 2015). "In contrast to TNFα, which failed to be associated to mortality or cardiovascular events in CKD, both circulating receptors are potential biomarkers in chronic kidney disease as predictors for outcome, be it in selected populations with diabetic nephropathy or in early or moderate CKD." (PMID 25823004, 2015). "The inflammatory pathway driven by TNF-α, through its receptors TNFR1 and TNFR2, is a common feature in the pathogenesis of chronic kidney disease (CKD), regardless of the initial disease cause." (PMID 36979469, 2023). "In addition, elevated levels of inflammatory markers, interleukin-6 (IL-6), tumor necrosis factor-alpha (TNF-α), and C-reactive protein (CRP) in patients with chronic kidney disease (CKD) may induce oxidative stress, thereby accelerating the progression of renal damage." (PMID 38004033, 2023). "Interestingly, TNF-α, IFN-γ, and IL-1β levels remained nonstatistically associated with death in the multivariable analysis that included the entire patient cohort after adjusting for age, chronic kidney disease, and receipt of immunomodulatory medications." (PMID 33232303, 2021). "In addition, it was mentioned that, in an adenine-induced chronic kidney disease rat model, the intervention of chrysin had a protective effect on the kidneys by reducing the concentration of serum creatinine (CRE), blood urea nitrogen (BUN), and tumor necrosis factor alpha (TNF-α)." (PMID 33917369, 2021). "One clinical trial tested the effects of MSC-derived EVs on the progression of chronic kidney disease (CKD) patients, and the results indicated that EVs can improve the estimated glomerular filtration rate (eGFR); decrease Scr, BUN, and TNF-α levels; and increase IL-10 levels." (PMID 31900218, 2020).
acute kidney injury (238 papers, 2004 to 2026). Sudden and sustained deterioration of the kidney function characterized by decreased glomerular filtration rate, increased serum creatinine or oliguria. "This oxidative stress is linked to renal failure and triggers an initial inflammatory response mediated by proinflammatory mediators TNF-alpha and IL-1b, and a transcriptional factor, NF-κB." (PMID 35056564, 2022). "Tumor necrosis factor (TNF-α) is implicated in the pathogenesis of acute nephrotoxin-induced renal failure as well as other forms of kidney damage." (PMID 34784920, 2021). "For example, TNFα has been linked to apoptosis and related cell death within the injured spinal cord, and in renal tissue, it is associated with renal failure." (PMID 34417952, 2021). "XIST silencing reduces the levels of TNF-α and IL-6 in a rat acute kidney injury model caused by I/R." (PMID 33299380, 2020). "CRRT with the oXiris filter seemed to allow effective removal of endotoxin and TNF-α, IL-6, IL-8 and IFNγ in patients with septic shock-associated acute renal failure." (PMID 31369593, 2019). "In rats with renal failure, neutralization of TNF-α decreased NFκB activity that was associated with an improvement of nitric oxide released by reduction in renal transforming growth factor beta 1 and endothelin-1 production." (PMID 29636702, 2018). "The most recent development in the area of ultrasensitive fluorescence detection using ZnO NRs pertains to the multiplexed detection and quantification of two urinary biomarkers, TNF-α and IL-8, in patients at risk for acute kidney injury (AKI)." (PMID 28241443, 2017). "Fatal outcome from pulmonary hemorrhages was associated with low TNF-α, high IL-1β, and high iNOS expression, a pattern possibly expressed also in dogs with other forms of acute kidney injury." (PMID 26824356, 2016). "We have previously shown that tumor necrosis factor (TNF) plays a crucial role in lipopolysaccharide (LPS)‐induced acute kidney injury, in part by causing injury to the renal endothelium through its receptor TNFR1." (PMID 26634902, 2015). "In some occasion of catabolic status, the chronic inflammation associated with renal failure often can lead to elevated levels of TNF-α and IL-6." (PMID 22761655, 2012). "Serum resistin concentrations were closely correlated to inflammatory parameters such as C-reactive protein, leukocytes, procalcitonin, and cytokines such as IL6 and TNF-α, as well as associated with renal failure and liver synthesis capacity." (PMID 19545363, 2009). "Increased tumor necrosis factor (TNF)-α levels are often associated with renal failure and injury." (PMID 36552226, 2022). "TNF-α, which causes inflammatory cell injury, can significantly induce the expression of the apo-A4 protein, which is also associated with pro-inflammatory acute kidney injury in human kidney cells." (PMID 32575412, 2020). "Renal failure was significantly associated with elevation of IL-21 and IL-23, while patients with liver involvement had a significant elevation of IL-21, IL-23, and TNF-α." (PMID 30123395, 2018). "Furthermore, it has been reported that mast cell-deficient mice exhibit attenuated acute kidney injury with cisplatin which is associated with reduced serum TNF-α levels and reduced recruitment of leukocytes to the inflamed kidney." (PMID 27822777, 2016). "Additionally, proinflammatory cytokines such as TNF-α, IL-6, and IL-1β have been shown to be associated with cisplatin-induced acute renal failure." (PMID 24171038, 2013). "Endothelial cell damage, circulating immune complexes, complement activation, T-cell activation, and cytokine response with high levels of tumor necrosis factor-α and interleukin-6 might cause acute renal failure and peripheral consumption of platelets." (PMID 15496243, 2004). "Also, polymorphisms of TNF alpha were seen as predictive of acute kidney injury." (PMID 41155766, 2025).
acute kidney injury (continued). "Acute kidney injury is characterized by a high inflammatory state, reduced cytokine clearance, and elevated levels of systemic cytokines, such as interleukin (IL)-17A, IL-6, IL-8, IL-1β, IL-12, and tumor necrosis factor (TNF)-α, which aggravate lung injury and increase the risk of lung infection." (PMID 39724279, 2024). "Some studies have demonstrated that TNF-α gene polymorphisms are associated with acute kidney injury (AKI), chronic renal failure (CRF), and ESRD." (PMID 34501555, 2021). "Many recent studies have reported that betanin supplementation reduces the levels of inflammatory cytokines such as TNF-α, IL-1β and IL-6 in various conditions, from stomach ulcers to testicular toxicity, from acute kidney injury to alcoholic liver disease." (PMID 41515203, 2025). "Acute kidney injury is triggered by the production of harmful free radicals and inflammatory processes, with elevated levels of inflammatory cytokines like TNF-α, IL-6, and IL-1β." (PMID 39093465, 2025). "In a lipopolysaccharide (LPS)-induced murine acute kidney injury model, simvastatin alleviated tubular necrosis and hypoxia by inhibiting the elevation of tumor necrosis factor-α (TNF-α)." (PMID 40620675, 2025). "Histological analysis showed kidney lesions, disrupted serum biomarkers (blood urea nitrogen and creatinine) related to acute kidney injury, and elevated pro-inflammatory mediators (IL-1β, IL-6, TNF-α)." (PMID 39217203, 2025). "The high TNF-α levels across multiple organs, including the heart and kidneys, highlight its role in both septic cardiomyopathy and acute kidney injury (AKI)." (PMID 39594987, 2024). "The incidence of renal insufficiency in HS patients with amyloidosis is reported as 44.4% (which seems very high), and TNF inhibitors particularly adalimumab were found to have favorable outcomes in avoiding renal failure in a review article." (PMID 39229360, 2024). "In a mouse model of cecal ligation and puncture (CLP)-induced sepsis, exosomal miR-93-5p inhibited lysine-specific demethylase 6B (KDM6B), reducing TNF-α production and acute kidney injury (AKI)." (PMID 38534389, 2024). "Signaling pathways involving the adenosine receptor encoded by Adora2b have been reported to exert protective effects during acute kidney injury by inhibiting neutrophil-dependent tumor necrosis factor-alpha release." (PMID 37125041, 2023). "The treatment with SeNPs coated with lycopene markedly halted the rise in the levels of TNF-α, IL-1β, IL-6, and gene expression of nitric oxide synthase in acute kidney injury-mediated renal inflammation." (PMID 37902021, 2023). "Ori has been shown to ameliorate acute kidney injury by inhibiting macrophages-mediated inflammation, and suppressing the expression of cytokines IL-2, IL-4, IL-6, IL-10, and TNF-α, suggesting that Ori had a potent anti-inflammatory response activity." (PMID 37375489, 2023). "In the plasma of burn-induced septic acute renal failure patients, TNF was detected, which is an established pro-apoptotic mediator." (PMID 37542608, 2023). "Previous studies have proved that acute kidney injury induced by TNF-α in DDP is closely related to a variety of cytokines in the kidney." (PMID 35355712, 2022). "In EHF patients, Hantavirus can work together with TNF- to stimulate the synthesis of ERK1/2, causing proteinuria and renal failure." (PMID 35663983, 2022). "A number of kidney injuries induce inflammation with elevated TNF levels, including acute kidney injury, renal ischemia/reperfusion injury, diabetic nephropathy, obstructive renal injury, and cisplatin-induced injury." (PMID 35685285, 2022). "In acute kidney injury model, anti-TNFα, antioxidant activities and acute pharmacologic activation of SIRT1 induces reno-vasodilatation, increases renal blood flow (RBF) and decreases RVR." (PMID 33513830, 2021). "si-PVT1 diminished levels of TNF-α, IL-6 and IL-1β in lipopolysaccharide-induced HK-2 cells, thus alleviating inflammation and acute kidney injury." (PMID 34775377, 2021).
acute kidney injury (continued). "METs can be induced by PMA, LPS, TNF-α, and other factors, and participate in the response to bacteria and toxins, as well as pathological processes such as acute kidney injury." (PMID 34925357, 2021). "In vivo, dexamethasone also showed a protective effect on acute kidney injury by preventing microvascular endothelial glycocalyx degradation initiated by TNF-α during SAP." (PMID 34433425, 2021). "This study emphasizes a critical role for TNF-α in mounting the inflammatory response during methotrexate nephrotoxicity and the ensuing kidney tissue damage and acute renal failure." (PMID 32083987, 2020). "The evaluation of different inflammatory mediators such as TNF-α, IL-1β, IL-6 and NF-κB verified the protective effects of linalool (50 and 100 mg/kg) against cisplatin-induced acute kidney injury." (PMID 33126443, 2020). "The levels of IL-8, MIP-1α, and TNF-α were significantly higher in patients with renal failure in comparison with patients with normal renal function." (PMID 32587468, 2020). "In the same line, in a model of acute kidney injury induced by cisplatin, MCs aggravated the disease-enhancing TNF production by the rapid release of TNF, which in consequence enhanced the injury-associated inflammatory response and leukocyte recruitment." (PMID 33396702, 2020). "The protein level of TNF-α has also been estimated to increase in the brain during acute kidney injury." (PMID 32850914, 2020). "To assess direct tissue injury, we measured kidney mRNA expression of KIM‐1 and NGAL, which are elevated in renal failure, and the inflammatory markers IL‐6, IL‐1β, and TNFα." (PMID 31102342, 2019). "According to our results, betaine has protective effects on isoprenaline‐induced renal failure via a decrease in TNF‐α level and nitric oxide synthase." (PMID 30811871, 2019). "The anti-malarial drug, hydroxychloroquine, was shown to markedly reduce the levels of pro-inflammatory cytokines (IL-1β, IL-6, and tumor necrosis factor alpha [TNF-α]) because it exerts its anti-inflammatory effects in the treatment of acute kidney injury." (PMID 31422287, 2019). "Compared to TNFR1 knockout mice, TNFR2 deficient animals showed reduced serum and kidney levels of TNF-α and were less susceptible to CDDP-induced TNF-α-driven renal failure." (PMID 30866950, 2019). "The interaction between NPs and cytokines was demonstrated by the administration of ANP to rats with acute kidney injury induced by I/R where it inhibited mRNA expression of TNF-α, IL-1β, and IL-6 in the lung and kidney." (PMID 29774097, 2018). "Several necroptotic pathways have recently been discovered in renal cells, depending on the initial stimulus, such as calcium crystals, cadmium, and TNF-α, or on the type of acute kidney injury." (PMID 29208768, 2018). "A clinical study showed that after administration of Huangqi injection to patients with renal failure, the secretion of both NO and TNF-α from the macrophages isolated from their dialysate was enhanced upon LPS induction." (PMID 29250558, 2017). "NF-κB is a well-known regulator of the transcription of inflammatory gene including TNF-α, IL-1β, and IL-6 during acute kidney injury." (PMID 28465474, 2017). "It has previously been reported that acute intraperitoneal or intravenous administration of endotoxin (lipopolysaccharide) in rodent models can induce acute renal failure through stimulation of toll-like receptor-type 4 and tumor necrosis factor." (PMID 27955691, 2016). "The compound TDZD-8, which targets and inhibits glycogen synthase kinase-3β, protects against endotoxemic acute renal failure mainly by down-regulating pro-inflammatory TNF-α and RANTES." (PMID 26104320, 2015). "The purpose of this study was to determine correlations between serum TNF-α concentration and indices of azotaemia (serum urea and creatinine concentration), renal failure indices and blood pressures in dogs infected with B. canis." (PMID 24553975, 2014).